TGFB1 (transforming growth factor beta 1)
Diseases named in the same sentence as TGFB1 in open-access papers (continued):
Sharing a sentence is not in itself a finding about the gene and the disease.
liver fibrosis (continued). "This pattern was further supported by the statistically significant association between the expression levels of these genes with that of AFP (α-fetoprotein), TIMP1 (tissue inhibitor of metalloproteinase 1) and TGFB1 (transforming growth factor β1), which are known markers of liver fibrosis." (PMID 34440687, 2021). "In this regard, Kuppfer cell activation leads to the production of many inflammatory cytokines, such as transforming growth factor beta 1 (TGF-b1), nuclear factor kappa-light-chain-enhancer of activated B cells (NF-Kb), and interleukin 1 beta (IL-1 β), related to the liver fibrosis process." (PMID 33187340, 2020). "TGFβ1 signaling is the main regulatory mechanism in liver fibrosis." (PMID 32373112, 2020). "In addition, acetaldehyde has been shown to be fibrogenic by upregulating the transcription of collagen I directly as well as indirectly by inducing the synthesis of transforming growth factor beta 1 (TGF-β1) in alcohol-induced hepatic fibrosis." (PMID 32932651, 2020). "Hepatic macrophages might induce liver fibrosis by promoting stellate-cell activation in the presence of continued injury through TGFb1 paracrine stimulation." (PMID 30631109, 2019). "During liver fibrosis, hepatic stellate cells (HSCs) and Kupffer cells (KCs) act as the initial effectors of collagen deposition and inflammation modulation with the aid of the pro-fibrogenic cytokine transforming growth factor beta 1 (TGF-β1)." (PMID 28535799, 2017). "TGFβ1, STAT1, and CXCR46, 13, 25 have previously been implicated in liver fibrosis." (PMID 28262670, 2017). "Our results demonstrate that hepcidin prohibits liver fibrosis by suppressing TGFβ1–Smad3 pathway in HSCs, which may depend on PI3K/Akt signalling elicited by FPN deficiency." (PMID 28004654, 2016). "Furthermore, it has been demonstrated that liver fibrosis from late radiation effects correlated with the increase in intracellular TGFβ1 levels." (PMID 26785338, 2015). "In addition to liver fibrosis, TGFβ1 serum levels were recently examined to determine the extent of fibrosis in breast cancer patients following radiation." (PMID 26785338, 2015). "Thus, at least part of the observed reduction in hepatic fibrosis in the PP2Acα knockout mice can be accounted for by a decrease in TGFβ1/Smad signaling." (PMID 25710025, 2015). "We have also observed increased enrichment of the histone modifications in the patient at the start of the genes for platelet derived growth factor (PDGF) and for transforming growth factor (TGFβ1), which are both known to mediate hepatic fibrosis, a well-known component of ASH." (PMID 24206787, 2013). "TGFβ1 bound its receptor, phosphorylated Smad3, and accelerated liver fibrosis." (PMID 22471627, 2012). "Thus, the TGFβ1 signal transduction pathway has become a new effective target for the prevention and treatment of hepatic fibrosis." (PMID 22471627, 2012). "We then explored if hAEC secreted factors acting directly on HSC could contribute to the reduction in hepatic fibrosis and TGFβ-1." (PMID 22719909, 2012). "Evidence from studies of fibrotic disorders, including renal and liver fibrosis, supports that TGFβ1 may play a novel role in fibrogenesis by promoting epithelial-mesenchymal transition (EMT) and activating fibroblasts to myofibroblasts." (PMID 17883846, 2007). "Additionally, in an in vitro model of liver fibrosis based on transforming growth factor beta 1 (TGF-β1)-activated HSCs cultured in a monolayer, we demonstrated that EVs derived from HLSCs and BM-MSCs can effectively downregulate the expression of αSMA and COL1A1 in activated HSCs." (PMID 39200313, 2024). "Moreover, TGFβ1 is described as a stronger signal that can regulate cell plasticity, inducing EMT-associated modifications of different liver cell populations, including hepatic stellate cells and hepatocytes, thus contributing to liver fibrosis." (PMID 37072829, 2023).
liver fibrosis (continued). "However, chronic liver damage leads to persistent high levels of TGFβ1, which induces the transactivation of hepatic stellate cells that produce excessive amounts of extracellular matrix proteins giving rise to liver fibrosis that may progress to cirrhosis." (PMID 37798809, 2023). "Hepcidin also ameliorates liver fibrosis by inhibiting hepatic stellate cells (HSCs)’ activation, which facilitates liver fibrosis via the degradation of ferroportin in HSCs, increasing Akt phosphorylation and finally prohibiting TGFb1-inducible Smad3 phosphorylation." (PMID 37628834, 2023). "Expression of Col1a1, a major component of collagen, and of Tgfb1 an important promoter of fibrosis was also stronger following administration of the WD in WT mice compared with Pla2r1 KO mice, further supporting that Pla2r1 KO mice were protected from liver fibrosis." (PMID 37667516, 2023). "Additionally, in a study performed by D’Argenio at al., treatment with GE reduced CCl-induced liver fibrosis leading to reduction of oxidative and endoplasmic reticulum stress and regeneration of the liver through the transforming growth factor beta 1 (TGF-β1) signaling pathway." (PMID 35056399, 2022). "Liver fibrosis monitored by the accumulation of α-Sma, collagen I, desmin, and Sirius red staining, as well as by measuring the mRNA levels of α-Sma, Col1a1, Mmp-3, and Tgfβ1, was significantly decreased by KY19334 treatment compared to treatment with selonsertib or ocaliva." (PMID 36114279, 2022). "Thus, we inferred that myricetin may reduce liver fibrosis induced by S. japonicum infection by regulating the TGFβ1/Smad/ERK and PI3K/Akt signaling pathway." (PMID 32373112, 2020). "Our study showed that myricetin suppressed the expression of TGFβ1, phospho-Smad2, phospho-Smad3, phosph-ERK1/2, Akt, phospho-Akt in schistosome-infected mice, revealing that myricetin may reduce liver fibrosis in schistosome-infected mice by inhibiting TGFβ1/Smad/ERK and PI3K/Akt signaling." (PMID 32373112, 2020). "Interestingly, Gal-3 knock-out mice displayed significantly decreased liver fibrosis with reduced expression of Tgfβ1, Acta2 and Col1a1 vs. WT following bile duct-ligated to induce experimental live fibrosis, suggesting that Gal-3 also played important roles in liver fibrosis." (PMID 32139740, 2020). "Although TGFβ1 transcription was reported to be Smad3-dependent, the undetectable decrease of TGFβ1 mRNA expression in NPLC0393 treated liver fibrosis mice might be due to the other signaling pathways besides TGFβ-Smad3, which are also involved in TGFβ1 expression." (PMID 21151953, 2010). "Our study reveals that KLB suppresses LSEC EMT induced by liver-stage schistosomula and TGFβ1 secretion, thereby inhibiting HSC activation and reducing liver fibrosis." (PMID 42154778, 2026). "TGFβ1 plays a crucial role in HSC activation and the progression of liver fibrosis through a SMAD‐dependent mechanism." (PMID 40060764, 2025). "Through gain- and loss-of-function experiments, we show that Gdf10 overexpression attenuates liver fibrosis by competitively binding TβR2, blunting SMAD2/3 phosphorylation, and suppressing TGFβ1-driven ECM deposition." (PMID 41281741, 2025). "TGFβ1, a group of protein polypeptides with multiple biological functions, was found to be regulated by FCD, contributing to the reduction in hepatic fibrosis." (PMID 38790823, 2024). "It was shown that oxymatrine can reduce the secretion of transforming growth factor beta 1 (TGF-β1) by downregulating HMGB1, leading to the inactivation of TGF-β1-mediated HSC activation, thereby effectively alleviating CCl4-induced liver fibrosis." (PMID 39354529, 2024). "In contrast, Col1A1, Timp1, and Tgfβ1 decreased, and Stat1 increased in both mRNA and protein levels following KIF18A overexpression in liver fibrosis models." (PMID 38372748, 2024).
liver fibrosis (continued). "While the role of TGFβ1 in HSC activation is well established, our model showed how its concentration, the number of stimuli and their periodicity influence the dynamics of liver fibrosis." (PMID 39074160, 2024). "This polyphenol can also act on transforming growth factor beta 1 (TGF-β1)/SMAD3, reducing liver fibrosis." (PMID 39458995, 2024). "We found that increased liver fibrosis in OVX Prmt6 KO mice fed alcohol correlated with elevated mRNA levels of Col1a1, Tgfb1, and Tnf, similarly to WT OVX mice." (PMID 38704651, 2024). "EMT, induced by factors such as transforming growth factor β1 (TGFβ1) produced during HCV infection, facilitates the transition of hepatocytes to myofibroblasts, leading to ECM production and liver fibrosis." (PMID 39000296, 2024). "We performed real-time PCR for Tgfβ1, Tnfα, Colα1, Pdfgrs, Timp-1, CCND2, and Mycn, the key factors for NASH, liver fibrosis, and liver tumor in WT, the dKO, and the tKO mouse livers." (PMID 37586586, 2023). "In NASH, TGFβ-1 stimulates the expression of α-SMA, which increase the levels of extracellular matrix proteins such as Fn and collagens, accelerating hepatic fibrosis." (PMID 36742397, 2023). "The potential application of mLO(-DAPT/D3) for the modeling of liver fibrosis was then examined after sustained exposure to a fibrosis-inducing cytokine cocktail (FIC, a mixture of TGFβ1, TNFα, IL-6, and IL-1β)." (PMID 36737811, 2023). "Together with the fact that these cells overexpress TGFB1, our results suggest that rNK cells in end-stage PSC contribute to liver fibrosis progression." (PMID 37063898, 2023). "PE-treated HSC significantly attenuated TGFβ1-mediated upregulation of collagen 1α1 and PDGFR α and β, which are key factors for liver fibrosis." (PMID 37586586, 2023). "To validate the expression of NG2 in vitro, we treated primary BMSC with TGFβ1, which is an important regulator of BMSC differentiation to MF during liver fibrosis." (PMID 36674693, 2023). "TGFβ-1 is the most potent fibrogenic cytokine and a key driver of HSC activation and liver fibrosis." (PMID 36742397, 2023). "Sorafenib, which has been reported to ameliorate liver fibrosis by reducing the expression of α-SMA, TGFβ1, and P-STAT3, was used as a positive control in this study." (PMID 35517817, 2022). "More specifically, losartan decreased transforming growth factor beta 1(TGF-β1) plasma levels, a known marker of hepatic fibrosis." (PMID 35448486, 2022). "Studies have shown that TGFβ1 crosstalks with BMP7, BMP9, and SMAD1/5/8, all of which can affect liver fibrosis 45-47." (PMID 33754025, 2021). "MFN2 inhibits transforming growth factor-beta 1 (TGF-β1)/Smad signaling and the formation of type I, type III, and type IV collagen, thereby ameliorating liver fibrosis and suppressing immune cell infiltration." (PMID 34482801, 2021). "In summary, the present study uncovered that A‐FABP potentiates liver fibrosis by enhancing LSEC capillarization and acting as a paracrine factor to exaggerate TGFβ1 production in HSCs." (PMID 34105268, 2021). "To investigate its potential role in the observed development of liver fibrosis in the NIF mice, we analyzed the kinetics of the mRNA expression of the Tgfb1 gene." (PMID 33311540, 2020). "The present studies showed the influences of SREBP1c on both receptors for TGFβ1 and PDGFβ, the most important cytokines for inducing HSC activation and liver fibrosis, and on their downstream signalling pathways of Smad3 and Akt1/2/3 in HSCs." (PMID 32678475, 2020). "The present review is focused on the interrelated molecular effects between AGAP2 and TGFβ1 expression, presenting AGAP2 as a new player in the signaling of this pro-fibrotic cytokine, thereby contributing to the progression of hepatic fibrosis." (PMID 32092977, 2020). "TGFβ1 and PDGFβ are identified as the most important cytokines for inducing HSC activation and liver fibrosis." (PMID 32678475, 2020).
liver fibrosis (continued). "Our data show that liver fibrosis is accompanied by higher production of OPG in liver tissue, particularly in response to TGFβ1." (PMID 32455750, 2020). "WNT-5A is a WNT family member that activates the non-canonical WNT pathways, and importantly it plays a relevant role in TGFβ1 mediated HSC activation and liver fibrosis." (PMID 33322158, 2020). "Macrophages also secrete profibrogenic transforming growth factor beta 1 (TGF-β1), a potent activator of HSCs leading to liver fibrosis." (PMID 31052525, 2019). "We demonstrate that NV556 decreased liver fibrosis in both STAM and MCD in vivo models and decreased collagen production in TGFβ1-activated hepatic stellate cells in vitro." (PMID 31717385, 2019). "After being activated by IL-33, hepatic MC releases numerous inflammatory mediators, among which transforming growth factor-beta 1 (TGF-β1) and IL-13 are correlated with liver fibrosis." (PMID 31632941, 2019). "HSCs are the pre-eminent matrix-producing cells in liver fibrosis, potently secreting TGFB1 and PDGF, thus mediating liver fibrosis as well as hepatocyte proliferation." (PMID 29855567, 2018). "SMAD3 is a key of signal transduction pathways in liver fibrosis and elevated STAT3 phosphorylation in fibrosis is combined with TGFβ1 and SMAD3 activation." (PMID 30346985, 2018). "Western blot analysis revealed that TGFβ1, α-SMA, p-Smad3, and p-ERK1/2 protein expression levels in DMN-induced liver fibrosis group were significantly higher than those in the control group." (PMID 30337590, 2018). "Several studies shows that dystroglycan is expressed on the membrane of hepatic stellate cells and is up-regulated by TGFβ1 and PDGF during liver fibrosis." (PMID 28117422, 2017). "We investigated the relationship between TM4SF5-positive TEMs with liver fibrosis and tumorigenesis, using normal Chang hepatocytes that lack TM4SF5 expression and chronically TGFβ1-treated Chang cells that express TM4SF5." (PMID 25033048, 2014). "The SFN incubation inhibited TGFβ1-induced SMAD3 phosphorylation in human hepatic stellate cell line, and mice treated with SFN were protected from hepatic fibrosis following bile duct ligation." (PMID 24691097, 2014). "A recent work has implicated TLR4, as expressed on hepatic stellate cells (HSCs), as a key driver of liver fibrosis, owing to the stimulatory effect of TLR4 activation on the transforming growth factor β1 (TGFβ1) pathway." (PMID 23441159, 2013). "LPS regulated TGFβ1-induced signals from HSC in TLR4/MyD88 in a dependent manner, thus modulating liver fibrosis in NASH." (PMID 23441159, 2013). "Moreover, in rats with liver fibrosis, it can reduce VEGFA, angiotensin I, and transforming growth factor beta 1, as well as the expression of its signal transmission medium, exert antiangiogenic effects by alleviating oxidative stress." (PMID 40550087, 2025). "TGFβ1 is considered the most important regulatory factor in promoting the formation of liver fibrosis In addition to regulating the classical Smad pathway, TGFβ1 also activates p38 MAPK signaling pathway to mediate liver fibrosis and HSC activation." (PMID 39407108, 2024). "By 2 weeks after alcohol cessation, Tgfb1, Tnf, and Ccl2 were decreased to the levels of control-fed mice (high-fat diet without alcohol) that do not develop liver fibrosis by Sirius red staining." (PMID 37943941, 2024). "Compared with the alcohol group, ADAM8 mRNA and protein expression, cell viability, and the expression of liver fibrosis markers and MAPK signaling pathway-related factors (p-ERK1/2, PCNA, Bcl-2, p-c-Jun, TGFβ1, p–p38 MAPK and HSP27) reduced significantly in the si-ADAM8-2 group." (PMID 39407108, 2024). "In addition, ketanserin reduced transforming growth factor-beta 1 (TGF-β1) and pro-collagen type I N propeptide (PINP) in a mouse model of liver fibrosis induced by CCl416." (PMID 38228622, 2024).
liver fibrosis (continued). "A recent study demonstrated that TGFβ‐2, but not TGFβ‐1 has a critical non‐redundant role in promoting lung and liver fibrosis." (PMID 37859621, 2023). "Furthermore, the neutralization of TGFβ using fresolimumab (GC1008), a human anti-TGFβ1 monoclonal antibody, has shown successful suppression of liver fibrosis development in mouse models." (PMID 37957462, 2023). "TGFβ1, which drives the transdifferentiation of phenotypical HSCs from quiescence to activation through paracrine and autocrine mechanisms, plays a critical role in the progression of HSC activation and liver fibrosis." (PMID 35517817, 2022). "Another study has shown that miR-21 may play a role in liver fibrosis with HBV etiology, mediated via transforming growth factor beta 1 (TGF-β1) signaling." (PMID 36142450, 2022). "Furthermore, Art inhibited transforming growth factor-beta 1 (TGF-β), and the SMAD signaling pathway mediates the development of liver fibrosis." (PMID 35586049, 2022). "Further review of the literature showed that both TGFβ1 and AngII could upregulate the expression of NOX4, and GKT137831, a dual inhibitor of NOX1/4, could inhibit the production of ROS and hepatic fibrosis." (PMID 34135982, 2021). "In line with the histological analysis, results from the mRNA expression of pro-fibrotic genes (including Acta2, Col1a1, Col1a2, and Tgfb1) further demonstrated that prophylactic but not therapeutic administration of OCA were effective against liver fibrosis." (PMID 31932588, 2020). "TGFβ1 signaling to PI3Kγ/AKT/RAC1 or through RAC1/ROS mediates cell migration of hepatic stellate cells in liver fibrosis or invasiveness of PDAC cells, respectively, whereas TGFβ/Smad3 signaling through DOCK4 and RAC1 facilitates lung adenocarcinoma metastasis." (PMID 33266416, 2020). "In addition, rottlerin treatment also suppressed TGFβ1-induced expression of ACTA2, COL1A1, COL1A2, and CCL2, the expression of which is greatly increased in HSCs of liver fibrosis patients." (PMID 32210801, 2020). "As crosstalk between SMAD3 and STAT3 in numerous biological functions is well documented, and because TGFβ1 can activate STAT3, which also has a role in liver fibrosis, we hypothesized that STAT3 may contribute to the antifibrotic effects of rottlerin." (PMID 32210801, 2020). "We observed that CM414 abrogated the effects of TGFβ1 on the expression of WNT-5A, a prominent growth factor of the non-canonical WNT pathway involved in liver fibrosis and TGFβ1-mediated HSC activation." (PMID 33322158, 2020). "Several studies have shown that TGFβ1 plays pivotal roles in HSC activation and hepatic fibrosis." (PMID 32210801, 2020). "For example, the dysregulated lncRNAs including NONMMUT014792.2, NONMMUT031907.2, NONMMUT061096.2, NONMMUT047510.2 and ENSMUST00000185516 may be co-expressed with TGFβ-1, JAK3, and STAT1, which are reported to be important regulators of liver fibrosis." (PMID 33261628, 2020). "Accumulating progresses have been made in better understanding the underlying mechanisms of liver fibrosis with recent major investigations focused on the pathways including TGFβ1, Notch and Hippo, involved in initiating HCs apoptosis and EMT in the pathogenesis of liver fibrosis." (PMID 31695787, 2019). "Moreover, the amelioration of hepatic fibrosis by FBR treatment was partly mediated by hepatic mRNA expression levels of fibrosis‐related genes including αSMA, TGFβ1, and Col1A1." (PMID 31660146, 2019). "Given that the increase was approximately 1.24-fold, we further demonstrated the efficacy of our strategy by using the relative concentrations of Sunitinib to treat transforming growth factor-beta 1 (TGF-β1)-activated hepatic stellate cells LX2, the key fibrotic cell that drives liver fibrosis." (PMID 30577655, 2018).